TSG101 (tumor susceptibility 101)
Diseases named in the same sentence as TSG101 in open-access papers (continued):
Sharing a sentence is not in itself a finding about the gene and the disease.
tumor (continued). "Here, we demonstrated that cancer-specific byproduct TSG∆154-1054 stabilizes TSG101 protein, and thus it promotes tumor cell aggression in terms of proliferative, migratory, and metastatic activities." (PMID 30759747, 2019). "TSGΔ154-1054 therefore specifically enhances TSG101-stimulated cell proliferation, clonogenicity, and tumor growth in nude mice." (PMID 26811492, 2016). "Coexistence of TSGΔ154-1054 and TSG101, most prominently, accounts for the tumor cell aggressiveness including increasing capacity for colony formation, as well as enhancing tumor xenograft growth in nude mice, in addition to increased proliferation." (PMID 26811492, 2016). "TSG101, which was initially identified as a tumor suppressor gene, is also known to contrarily function as a tumor-enhancing gene." (PMID 26608825, 2015). "PC3, MDA-MB-231, and MCF-7 cells, where TSG101 has been reported to function as a tumor-enhancing gene, are derived from epithelial tissues." (PMID 26608825, 2015). "As for Tsg101, there is some evidence for a potential tumor suppressor role of another ESCRT-I subunit, Vps37A." (PMID 24641493, 2014). "Nevertheless, the association between Tsg101 and tumorigenesis made Tsg101 the best-researched ESCRT protein with regard to neoplasia." (PMID 24641493, 2014). "Fibroblasts isolated from TSG101-/- mouse embryos and tumor cells treated with siRNA directed against TSG101 have been reported to show reduction of the rate of cell growth." (PMID 24244542, 2013). "The generation of tumor models might have been hindered by the fact that in most cell types, the level of the TSG101 protein is tightly controlled by a posttranslational, autoregulatory feedback mechanism that is still poorly defined." (PMID 40624726, 2025). "However, given the low penetrance (18%) and very long tumor latency (1–2 years), the oncogenic potency of TSG101 appeared to be relatively weak." (PMID 40624726, 2025). "More than two decades after Tsg101 was first cloned and designated as a tumor susceptibility locus, there are no genetically engineered models that develop cancer in response to the overexpression or downregulation of this gene." (PMID 40624726, 2025). "For these reasons, in endometrial carcinogenesis, we decided to investigate the expression of TSG101 (a suppressor of tumor transformation) and LSF (a transcription factor involved in numerous cellular processes, such as cell cycle regulation, cell growth, development, and apoptosis)." (PMID 38607019, 2024). "The results showed that rotenone could induce tumor stem cells to express Tspan28, Tspan29, Tspan30, and TSG101." (PMID 38649381, 2024). "According to this network, we found that the exosome markers CD81, CD9, CD63, and TSG101 were associated with ANXA9, suggesting that ANXA9 may exist in exosomes in tumor tissues." (PMID 37294149, 2023). "The curated networks revealed that the multifunctional tumor susceptibility gene product TSG101 clusters with several other hits from the primary screen (Fig EV1D), implying a crucial biological function of TSG101 for DNA damage‐induced NF‐κB signaling." (PMID 36124865, 2022). "For example, the downregulation of TSG101 reduces exosome secretion in tumor and dendritic cells." (PMID 36076942, 2022). "In addition, we showed that the stabilized TSG101 protein promotes cell proliferation, clonogenicity and tumor growth in nude mice, and these observations are further reflected in the cellular invasion, migration and metastasis of NPC patients." (PMID 35269659, 2022). "Tsg101 was initially cloned as a candidate tumor suppressor gene in mice." (PMID 34271917, 2021). "Moreover, we checked the expression of contamination markers albumin, calnexin and Gm130 as well as another EV marker TSG101 in both EVs and tumor tissues by Western Blot as a quality control of EV isolation." (PMID 33391510, 2021).
tumor (continued). "The effective isolation of EVs was confirmed by western blot analysis, with positive signal for the tetraspanins CD9, CD63, CD81 and Tumour Susceptibility Gene 101 (TSG101), while negative for the cellular marker calnexin." (PMID 33216826, 2020). "Further ImageStream analysis revealed the expression of epithelial cell adhesion molecule (EpCAM) and exosome specific surface markers, including CD9, CD63, tumor susceptibility gene 101 (TSG-101), and CD81 confirming the tumor cell-derived vesicles as exosomes." (PMID 32456301, 2020). "Among the various aberrantly spliced TSG101 mRNAs, an isoform missing internal 901 nucleotides (termed TSG101∆154-1054 or TSG101∆190-1090, which lacks residues 204 to 1104 according to the latest RefSeq NM_006292.3) is predominant in most tumor tissues." (PMID 30759747, 2019). "Previous studies have identified TSG101 as an oncogene in various tumor types." (PMID 30675171, 2019). "In addition, we predicted and verified that the effect of TSG101 on the growth of tumor was related to elevated c-myc protein levels, accompanied by up-regulated cyclin E1/cyclin-dependent kinase 2 (CDK2) complex." (PMID 30675171, 2019). "Collectively, TSGΔ154-1054 stabilizing TSG101 prompts the development of tumor malignancy." (PMID 26811492, 2016). "Also, TSG101 deficiency causes cell cycle arrest at G1/S transition in primary embryonic fibroblasts and tumor cell lines in cell culture systems, and TSG101 depletion leads to reduced tumor cell clonogenicity, migration, and drug resistance." (PMID 26811492, 2016). "The functions of TSG101 in carcinogenesis and tumor progression have been controversial." (PMID 26608825, 2015). "Thus, a series of studies are shedding light on the molecular mechanism by which TSG101 functions as a tumor suppressor gene." (PMID 26608825, 2015). "Although previous studies have unraveled diverse biological functions of TSG101, the precise mechanism by which TSG101 is involved in carcinogenesis and tumor progression in a bidirectional and multifaceted manner remains unclear." (PMID 26608825, 2015). "Although further studies are necessary, TSG101 may play pathological roles as a tumor-enhancing gene in tumor cell types derived from epithelial tissues." (PMID 26608825, 2015). "In sheer contrast to these, a number of ESCRT-I, -II, -III mutations, such as those mapping to Tsg101, vps28, Vps25, vps20, when made homozygous in eye discs, display a Mutant Eye No Eclosion (MENE) phenotype that have been associated loss of tumor suppression in Drosophila." (PMID 24718108, 2014). "TSG101 (Tumor susceptibility gene 101) was identified initially in mouse cells in a genetic screen for loci that modulate neoplastic transformation of NIH3T3 fibroblasts and tumor formation in nude mice." (PMID 24244542, 2013). "Lastly, we investigated whether mesothelin resides in tumor-released exosomes, We immunoprecipitated mesothelin from tumor cell supernatants and looked by western blot for the presence of co-immunoprecipitated exosomal proteins TSG101 and ALIX." (PMID 22163010, 2011). "Also, numerous attempts to establish primary and immortalized TSG101-overexpressing tumor cell lines were unsuccessful likely due to the silencing of the MMTV-tTA and TetO-Tsg101 transgene expression in cultured tumor cells as determined by bioluminescence imaging (not shown)." (PMID 40624726, 2025). "Tumor susceptibility gene 101 (TSG101), initially identified as a tumor suppressor gene in fibroblasts and a microtubule-binding protein, has been found to exhibit dual functionality in some epithelial tumor cells, serving both as a tumor suppressor and a oncogene/protein in subsequent studies." (PMID 39551802, 2024). "In most instances, the protein content of CAF-EVs is comparable between different tumor types and includes proteins normally enriched in exosomes such as CD9, CD63 and CD81 and proteins involved in exosome biogenesis like ESCRT-associated proteins, Alix, TSG101, HSC70 and HSP90β." (PMID 33899109, 2021).
tumor (continued). "In evaluations of OS-SEV effects on distant metastasis based on lung specimens, mice bearing TSG101-KO cells had > 15-fold fewer metastatic foci and 6-fold smaller areas of metastatic lesions than those with WT cells, when the primary lesion of each tumor grew to identical sizes." (PMID 34017686, 2021). "Also, TSG101-KD treatment increased miR-130b-3p level in tumor tissues while reduced in the plasma." (PMID 33829013, 2021). "Additionally, angiogenesis was dramatically reduced by LM8-SEV suppression, as indicated by a 75% reduction in CD31-positive vessels and an approximate 75% reduction in VEGF-positive areas in mice bearing TSG101-KO cells, possibly contributing to the slow tumor growth of TSG101-KO cells." (PMID 34017686, 2021). "For example, a search for ‘Tumor susceptibility gene 101’ can return articles that do not have that term in the article title or abstract if at least one of the metadata sources has protein data related to the TSG101 protein for the article." (PMID 32507889, 2020). "Despite studies on cell lines that provide insight into the molecular underpinnings by which TSG101 might function as a negative growth regulator, a biologically significant role of TSG101 as a tumor suppressor has yet to be confirmed using genuine in vivo cancer models." (PMID 32075127, 2020). "In addition, TSG101 depletion in tumor cells reduces migration, clonogenicity, and drug-resistance." (PMID 30759747, 2019). "Thus, tumor cell-released Hsp70 and Hsp90 were associated with CD9/TSG101/AchE-positive EVs." (PMID 28928431, 2017). "Furthermore, we conceive that there may be a difference in pathological roles of TSG101 between tumor cell types derived from epithelial and mesenchymal tissues." (PMID 26608825, 2015). "Taken together with the results that depletion of neither TSG101 nor MMP-9 affected cell growth of HeLaS3 cells (data not shown), these results suggest that TSG101 may be implicated in the invasive potency of HeLaS3 cells as a tumor-enhancing gene." (PMID 26608825, 2015). "Specifically, HRS (ESCRT-0) and TSG101 (ESCRT-I) are upregulated in cancers and promote tumor progression." (PMID 40277928, 2025). "The western blotting analysis showed that the isolated exosomes from BNT162b2-transfected tumor cells carried not only exosome markers CD63 and TSG101, but also the SARS-CoV-2 spike protein and OVA protein." (PMID 39743545, 2025). "The violin diagram shows that in HNSCC tissue, macrophages highly expressed four classic marker genes (CD63, CD9, CD81, TSG101) of exosomes, suggesting that TAM-EVs are highly secreted in the tumor microenvironment." (PMID 38602536, 2024). "Upon staining vesicles for typical tumor biomarkers, the presence of surface receptors CD63, CD81, and TSG-101 was demonstrated." (PMID 37886937, 2023). "The results of Western blot analysis also showed that exosomes secreted from 4T1 tumor cells express CD81, CD9, CD63, and TSG101 markers along which β-actin was used as the internal control." (PMID 34194604, 2021). "We detected tumor-derived EVs in supernatants of LLC that were similar to exosomes in terms of size (~109 nm) and protein expression (Hsp70/TSG101/CD9)." (PMID 33510128, 2021). "When overexpressing miR-185-5p or interfering with RAB35, we observed suppressed TSG101 protein and CD63 protein expression in tumor cells and their derived exosomes." (PMID 34500436, 2021). "A seminal study of paired tumor tissues and CD63+/TSG101+ EVs from the serum of patients with pancreatic cancer reported that EV DNA covered the entire genome, and carried mutations that were identical to the parental tumors." (PMID 33158181, 2020). "Since the TSG101 protein has a critical role in cell clonogenicity and migration, we next investigated the effects of TSG∆154-1054 expression in tumor cell migration by wound healing assay examined by bright-field microscopy." (PMID 30759747, 2019).
tumor (continued). "Next, we analyzed the correlation between TSG101 and PEG10 and found that there was a direct correlation between TSG101 and PEG10 levels in non‐tumour tissues and HCC patients (r = 0.63, P < 0.001)." (PMID 30450735, 2019). "In our present study, we detected the protein expression of TSG101 in HCC tissues and non‐tumour liver tissues." (PMID 30450735, 2019). "We discovered that TSG101 protein was expressed increasingly in the patients with HCC, comparing with the non‐tumour liver tissues." (PMID 30450735, 2019). "We detected tumor-released EVs from conditioned medium and serum that are consistent to exosomes in terms of size (~110 nm) and marker proteins (CD9/TSG101/AchE)." (PMID 28928431, 2017). "However, several recent reports have also demonstrated that TSG101 contrarily functions as a tumor-enhancing gene in some epithelial tumor cells, suggesting that TSG101 may play divergent roles in carcinogenesis and tumor progression in different cell types." (PMID 26608825, 2015). "Exosomes were collected from tumor cell culture media by ultracentrifugation Their identity was confirmed by electron microscopy and the presence of CD63, HSP70 and TSG101, known exosome specific markers." (PMID 26337469, 2015). "On the basis of our present finding that TSG101 depletion promoted cell invasion and MMP-9 expression in HT1080 cells, but contrarily reduced these events in HeLaS3 cells, TSG101 may be implicated in the invasive potency of tumor cells through regulating the expression of MMP-9." (PMID 26608825, 2015). "Cox’s multivariate analysis demonstrated that differentiation, tumor size (≥3 cm), TNM stage, lymph node metastasis, invasion, surgical procedure and TSG101- and PEG10-positive expression positively correlated with the poor survival rate of the AC patients." (PMID 24944680, 2014). "Overall, Hrs (ESCRT-0) and Tsg101 (ESCRT-I) seem to be mostly up- and Vps37A (ESCRT-I), Chmp1A and Vps4B mostly down-regulated in tumor samples." (PMID 24641493, 2014). "While differential effects of TSG101 isoforms on tumor development and progression have not been established, our results suggest that tumor associated isoforms that do not contain the central or SB domain of TSG101 would lack the ability of the full-length protein to repress the p21 promoter." (PMID 24244542, 2013). "The histological examination of residual cancer tissues of Dox-treated animals showed that the size of the tumor was not an accurate readout for the effects of the ablation of exogenous TSG101 (right)." (PMID 40624726, 2025). "A loss of contact inhibition and colony formation was observed when the Tsg101 cDNA was expressed in both antisense and sense orientation in NIH3T3 cells, suggesting that this gene might have tumor-suppressive and oncogenic properties." (PMID 40624726, 2025). "Further, immunohistochemical (IHC) analysis of tumor tissues confirmed that the combination of α-hederin and PTX significantly decreased the expression of SREBF1, FASN, phosphorylated SMAD2, and the sEVs-marker protein TSG101 compared to PTX alone." (PMID 38362150, 2024). "Tumor-derived exosomes (uniformly round or oval, size range of 30–120 nm, marker proteins CD81, CD63,TSG101) miR-146a-5p can activate the anti-oncogene WWC2-mediated Hippo-YAP signaling pathway and change the dynamics of F-actin/G-actin, eventually leading to CC metastasis." (PMID 39165926, 2024). "In addition, a low dose of TM decreases exosome production in carcinoma cells, and Xbp1 depletion significantly decreases the numbers of exosomes and exosome markers, such as TSG101 and CD63, produced from tumor cells." (PMID 37524131, 2023). "In addition, exosome-specific markers TSG101, CD9, CD63 and CD81 were evaluated in tumor-derived exosomes through different methodologies." (PMID 35804987, 2022). "Similarly, the expression of TSG101 and PEG10 in HCC tissues were significantly increased compared with the non‐tumour tissues, which was in line with our results found above." (PMID 30450735, 2019).
tumor (continued). "In addition, we assessed the expression and distribution of TSG101 and PEG10 in non‐tumour tissues and HCC patients by immunohistochemistry." (PMID 30450735, 2019). "The mechanism of action by TSG∆154-1054 was achieved through TSG101 stabilization, since TSG∆154-1054 failed to promote tumor cell migration once the cellular TSG101 protein was depleted by TSG101-specific siRNA." (PMID 30759747, 2019). "Additionally, TSG101 serves as a transcriptional co-regulator in suppressing transcription of nuclear hormone receptors and p21 (CIP1/WAF1) tumor suppressor gene." (PMID 26811492, 2016). "In sharp contrast to the previously proposed tumor suppressive role of this gene, mice that lack Tsg101 in various tissues including the mammary epithelium did not develop preneoplastic lesions and cancer." (PMID 22479596, 2012). "Therefore, we first purified the tumor cell-derived exosomes and verified them using NTA (NanoSight) and electron microscopy, then examined the exosome-expressed proteins (CD9 and TSG101) using WB." (PMID 40756343, 2025). "Stimulation of tumor cells by PMA has been reported to lead to increased levels of MMP-9 secretion through activating several signaling pathways, raising the possibility that TSG101 depletion leads to increased levels of MMP-9 secretion through amplifying these signaling pathways." (PMID 26608825, 2015). "TEX harvested from tumor cell supernatants by SEC had vesicular morphology, were sized at 50–200 nm (median = 105 nm), and carried CD9, TSG101, and ALIX but were negative for calnexin." (PMID 40121518, 2025).